PLCH2 (phospholipase C eta 2)
Description:
The production of the second messenger molecules diacylglycerol (DAG) and inositol 1,4,5-trisphosphate (IP3) is mediated by activated phosphatidylinositol-specific phospholipase C enzymes. This phospholipase activity is very sensitive to calcium. May be important for formation and maintenance of the neuronal network in the postnatal brain (By similarity).
Synonyms: PLC-L4; PLC-eta2; KIAA0450; PLCL4; PLCeta2; RP3-395M20.1
Tractability: Antibody: its Gene Ontology location is reachable by antibodies, with high confidence; UniProt places it where antibodies can reach, with medium confidence. PROTAC: ubiquitination databases record sites on it; its protein half-life has been measured.
Gene: Protein-coding gene on chromosome 1 (2,425,980 to 2,505,532, forward strand). Ensembl gene ENSG00000149527.
Subcellular location: Cytoplasm; Cell membrane
Pathways (Reactome):
Metabolism: Synthesis of IP3 and IP4 in the cytosol
Gene Ontology:
Molecular function: phosphatidylinositol-4,5-bisphosphate phospholipase C activity; calcium ion binding; phospholipase C activity; phosphoric diester hydrolase activity
Biological process: phosphatidylinositol metabolic process; phospholipase C-activating G protein-coupled receptor signaling pathway; positive regulation of 1-phosphatidyl-1D-myo-inositol 4,5-bisphosphate biosynthetic process; phosphatidylinositol-mediated signaling; release of sequestered calcium ion into cytosol; intracellular signal transduction; lipid metabolic process; signal transduction
Cellular component: cytoplasm; plasma membrane
Genetic constraint (gnomAD): Loss-of-function variants: 96 observed, 112.42 expected, observed/expected ratio (o/e) 0.85, 90% interval 0.72 to 1.01. The synonymous counts are far from expectation, so gnomAD's model fits this gene poorly and the ratio says little. Missense variants: 1,942 observed, 1,818.8 expected, observed/expected ratio (o/e) 1.07, 90% interval 1.03 to 1.11. Synonymous variants: 947 observed, 759.18 expected, observed/expected ratio (o/e) 1.25, 90% interval 1.18 to 1.32.
Homologues: Orthologues: chimpanzee PLCH2 (99% identical), macaque PLCH2 (95% identical), mouse Plch2 (83% identical), rat Plch2 (82% identical), guinea pig PLCH2 (80% identical), pig PLCH2 (79% identical), chimpanzee PLCH2 (72% identical), tropical clawed frog plch2 (65% identical), dog PLCH2 (64% identical), zebrafish plch2a (60% identical), zebrafish plch2b (36% identical), Caenorhabditis elegans pll-1 (23% identical), and 4 more. Paralogues in human: PLCH1 (50% identical), PLCL2 (26% identical), PLCL1 (26% identical), PLCD4 (23% identical), PLCE1 (22% identical), PLCD1 (21% identical), PLCG1 (21% identical), PLCG2 (20% identical), PLCB3 (20% identical), PLCB4 (20% identical), PLCD3 (20% identical), PLCB1 (19% identical), and 2 more.
Diseases named in the same sentence as PLCH2 in open-access papers:
PLCH2 is named in the same sentence as 9 diseases in open-access papers, as found by Europe PMC text mining. Sharing a sentence is not in itself a finding about the gene and the disease. The quoted sentences say what the papers report.
developmental delay (1 paper, 2008). "An example would be to speculate an association between the learning difficulties, developmental delay and speech delay identified in the proband with the deletion of PLCH2." (PMID 19019217, 2008).
glioma (1 paper, 2021). A benign or malignant brain and spinal cord tumor that arises from glial cells (astrocytes, oligodendrocytes, ependymal cells). "Finally, driver gene analysis of the immune types revealed that IDH1, IDH2, and PLCH2 are the major driver genes for glioma, clearly suggesting that they may be potential targets for mRNA vaccines." (PMID 34603319, 2021).
osteoarthritis (1 paper, 2024). A noninflammatory degenerative joint disease occurring chiefly in older persons, characterized by degeneration of the articular cartilage, hypertrophy of bone at the margins and changes in the synovial membrane. "Additionally, curcumin can exert therapeutic effects on osteoarthritis by targeting the PIP4K2C, INPP5J, ITPKA, ITPKB, ISYNA1, and PLCH2 proteins associated with inositol phosphate metabolism." (PMID 37938371, 2024).
vitiligo (1 paper, 2024). Generalized well circumscribed patches of leukoderma that are generally distributed over symmetric body locations and is due to autoimmune destruction of melanocytes. "Phospholipase C Eta 2 (PLCH2) expression was upregulated in stable vitiligo patients, and significant downregulation of leucine zipper protein 4 (LUZP4) in progressive vitiligo patients was seen." (PMID 38715599, 2024). "The mechanisms of how PLCH2 or LUZP4 could be involved in inflammation and vitiligo remains unclear." (PMID 38715599, 2024).
tumour (1 paper, 2024). "In particular, genes such as MTND1P23, PLCH2, RNF223, PERM1, TAS1R3, and specific TMEM genes exhibit varied levels of expression across different tumour stages, thereby presenting a potential to discern early-stage ESCC from its later stages." (PMID 38562378, 2024).
PLCH2 also shares sentences with these, for which no sentence is quoted: colorectal cancer (1 paper); Hypertension (1); leiomyoma (1); speech delay (1).